TNF (tumor necrosis factor)
Diseases named in the same sentence as TNF in open-access papers (continued):
Sharing a sentence is not in itself a finding about the gene and the disease.
tumor (continued). "Macrophage accumulation, oxidation of LDL-C, secretion of IL-1β, TNF-α and other inflammatory factors would promote formation of tumor plaques and inflammatory reactions." (PMID 31341840, 2019). "A wide variety of evidence has pointed to a pivotal role of TNF-α in tumor proliferation, migration, invasion and angiogenesis, including BC." (PMID 31632916, 2019). "On one hand, TNF is capable of inducing hemorrhagic necrosis and apoptosis of the tumor endothelial cells and also of cancer cells." (PMID 31799191, 2019). "They secrete inflammatory cytokines like IFN-γ, TNF-α and IL-6 that facilitate the development of anti-tumor immune responses." (PMID 31608067, 2019). "Here, tumour cells cultured on gelatine (control HT29 or shLAMA5) are serum starved at confluence for 7 days in the presence of 100 ng/mL TNF-α or a PBS control." (PMID 31064120, 2019). "In a Drosophila melanogaster malignant tumor model, early-stage tumor growth and invasion are genetically dependent upon tumor necrosis factor and interleukin-6 mediated autophagy within the local tumor microenvironment." (PMID 30741926, 2019). "Then, we assessed the secretion of cytokines important for anti-tumor T cells responses, namely TNFα, IFNγ and IL-2." (PMID 31500665, 2019). "TNF-α is a proinflammatory cytokine and plays a vital role in tumor malignancy, including motility, tumor cell invasion, and metastasis." (PMID 31068208, 2019). "The inaugural COTC trial evaluated a tumor vasculature targeted adeno-associated virus phage vector targeted to alphaV integrins expressed on tumor endothelium and delivering tumor necrosis factor (TNF), in preparation for human trials." (PMID 31803625, 2019). "Radiation is known to induce an inflammation response by damaging tumor endothelial cells and triggering inflammatory cytokine signaling (via Interleukin 1 and the tumor necrosis factor)." (PMID 31097034, 2019). "Although TNF is mainly produced by lymphocytes, it is also produced by tumor cells and affects cellular processes such as apoptosis, necrosis, angiogenesis, immune cell activation, differentiation, and cell migration." (PMID 31026363, 2019). "In the tumor inflammatory microenvironment mimicked by the 3D co-culture system, secretion of inflammatory cytokines IL-12p70 and TNF in the A549RR group was decreased compared with the A549 group (p<0.05)." (PMID 31417646, 2019). "TNFα, another cytokine known to activate the NF-κB pathway, whose activation contributes to tumor development, was also upregulated in tRXRα mice." (PMID 30931933, 2019). "Meanwhile, the downregulation of PDL1 expression increased IFN‐γ, IL‐2, and TNF‐α expressions in mouse serum and tumor tissue samples and decreased IL‐10 expression." (PMID 31557409, 2019). "TNF-α which is generated in the tumor microenvironment, modulates cancer cells, their surrounding stromal cells and the ECM in multiple cancers and acts as an autocrine and paracrine growth factor." (PMID 31341423, 2019). "Contact-independent tumor suppression is accomplished via different cytokines and chemokines such as tumor necrosis factor-alpha (TNF-alpha), IL-6, and TGF-beta released by fibroblasts." (PMID 31640297, 2019). "The biological rationale for combining anti-TNFα therapies with ICIs comes from recent insights into the role of TNFα in tumor immunology." (PMID 31439050, 2019). "This polarization actively suppresses tumor progression largely because of the release of TNF-α and IL-12 in co-culture conditions with tumor cells." (PMID 31216715, 2019). "In contrast, in some types of tumors, the tumor suppressive effects of TAMCs have been reported, mainly by supporting tumor rejection and mediating tumor cell apoptosis via the production of IL-4 and TNF-α." (PMID 30927923, 2019). "Th1 cells can induce the secretion of IL-1 beta and TNF-alpha by M1 macrophages and thus suppress the tumor." (PMID 31861498, 2019).
tumor (continued). "M1 TAM are activated with interferon-γ (INF-γ) and tumor necrosis factor-α (TNF-α) to provide a cytotoxic effect against tumor cells after the release of reactive oxygen species and nitric oxide." (PMID 30680411, 2019). "TNFα plays an important role in BV-6 induced cell death in many tumor cell lines and is expressed upon BV-6 stimulation in KGN." (PMID 31412918, 2019). "The tumours of mice treated with this triple combination therapy had increased frequencies of mature DCs and IFNγ+ and TNFα+ CTLs." (PMID 31091774, 2019). "N1 neutrophils reduce tumor immunosuppression through the production of several molecules, such as TNF-α, ROS (Reactive oxygen species), ICAM-1 (Intercellular Adhesion Molecule 1), and Fas." (PMID 31013961, 2019). "IL-2, IFN-gamma and TNF-alpha secretions were significantly reduced by continuous exercise in the tumor-bearing mice fed a high-fat diet." (PMID 31528182, 2019). "PGE2 downregulates TNF-α, inhibits T and B cells proliferation, and NK-mediated tumor clearance, while PGD2 favors T helper 2 cells activation at the expenses of tumor eradicating T helper 1 immune response." (PMID 31812953, 2019). "Pancreatic tumor-bearing mice receiving dCAR-T cells released higher levels of cytokines, including IL-2, IL-6, IFN-λ and TNF-α, and showed a marked reduction in tumor growth compared to controls receiving CAR-T cells alone." (PMID 30987642, 2019). "Then, the production of different cytokines (IFN-γ, IL-4, TNF-α and IL-17-A) by peripheral immune cells was evaluated at different time points after tumour irradiation." (PMID 31906092, 2019). "Our data identified that in response to tumor cell-derived IL-1β and TNF-α, astrocytes not only continued to express TGF-β2, but the expression increased significantly." (PMID 31602400, 2019). "The controversial role of TNF described in CRC is also observed in PDAC: albeit the TNF exposure of tumor-bearing mice increases tumor growth, TNF plays also antitumorigenic function through TNFR1." (PMID 31191652, 2019). "TNF-α is a multifunctional cytokine produced by activated immune cells, tumor cells or stromal cells in tumor microenvironment." (PMID 31109341, 2019). "Several gerokines are capable of modulating all stages of oncogenesis, from tumor initiation and growth to cancer invasion and metastasis, particularly TNF-α and IL-6." (PMID 30682077, 2019). "Tumor necrosis factor-alpha (TNF-α) is a pleiotropic cytokine involved in inflammatory processes and anti-tumor responses, including hematological malignancies." (PMID 30934014, 2019). "Despite being described as a tumor necrosis factor, it is known that this molecule is able to support tumor development and invasion." (PMID 31137684, 2019). "Tumor necrosis factor-alpha (TNFα), was initially reported to be a potent anti-tumor cytokine that can abrogate tumor growth." (PMID 31466313, 2019). "The classical activation of M1 macrophages induces the release of pro-inflammatory cytokines such as IL-12 and tumor necrosis factor (TNF), and thus plays a role in the killing of tumor cells." (PMID 31455032, 2019). "Accordingly, studies showed that upregulation of TNF-α in endothelial and immune cells promotes early tumor inflammation and stromal interactions that facilitate tumor invasion and metastasis." (PMID 31600735, 2019). "The data obtained from clinical studies have revealed that the expression level of TNF-α in the tumor tissues and serum samples obtained from patients with non-small cell lung cancer increased along with the clinical stage of the tumor." (PMID 31540489, 2019). "The therapeutic effect resulting from enhanced tumor-infiltrating DCs and macrophage infiltrate switching from M2 to M1 consequently produce increased IL-12 and tumor necrosis factor (TNF)." (PMID 32010123, 2019). "CAAs also secrete several adipokines, such as TNF-α, IL-6, and IL-8, which support tumor cell growth." (PMID 31277406, 2019).
tumor (continued). "The biological effects of L19-TNF on tumor cells, lymphocytes and tumor vessels were investigated with the aim to enable the administration of TNF doses, which would otherwise be lethal." (PMID 31803362, 2019). "In cancers triggered by viruses (e.g., cervical cancer) or by bacteria (e.g., stomach cancer), we would expect an activation of ILC1s, the production of IFNγ and TNFα, leading to anti-tumor immune responses." (PMID 31024531, 2019). "The interaction provoked NK cell activation and the secretion of IFN-γ and TNF-α, which induced tumor cell growth arrest, including in in vivo cancer models." (PMID 29740448, 2018). "Docetaxel caused an upregulation in pro-lymphangiogenic factors including VEGFC and TNF-α in the tumor microenvironment in vivo." (PMID 29976154, 2018). "We showed that select inflammation and tumor-burden biomarkers (TNFα, IL-1b, IL-12, and CYFRA 21-1) and baseline neutrophil count were associated with patient outcomes in univariate analysis." (PMID 29398577, 2018). "Recent studies have attributed tumor suppression by ΔppGpp Salmonella to a marked increase in production of proinflammatory cytokines, namely, TNF-a and IL-1b, by macrophages and dendritic cells infiltrated into the tumor mass." (PMID 29492216, 2018). "Monoclonal antibodies directed against TNF-α, VEGF, and IL-6 has shown promising results to ameliorate inflammation and cancer, while direct administration of IL-2 has been shown to cause tumor regression." (PMID 29662489, 2018). "Some of the cytokines such as IL-10 and TGF-β suppress the immune cell function and help tumor cells evade the immune system, while cytokines like IL-12, IFN-γ, and TNF-α support immunological functions by enhancing anti-tumor immunity." (PMID 30631327, 2018). "In general, effector cells rejected the tumor cells, accompanying with cytokine release, including IL-2, TNFα, IL-6, and IFNγ." (PMID 30103775, 2018). "It has been observed that the proinflammatory role of TNF-α becomes involved in all stages of tumorigenesis that include tumor cell transformation, survival, proliferation, invasion, angiogenesis, and metastasis." (PMID 30581847, 2018). "After GET, both TNFα and IL-12 mRNA levels significantly increased, resulting in a pronounced tumor growth delay of 27 days and a prolonged survival rate." (PMID 29468364, 2018). "Macrophages are activated to release TNF-α by neutrophil chemotactic factors and reactive oxygen species resulting in the elimination of tumor cells, however an uncontrolled pattern can promote cell laceration and necrosis." (PMID 30287783, 2018). "Multiple inflammatory cytokines, including IL-1β, IL-6, and TNF-α, increase proliferation and invasion of tumor cells." (PMID 30298062, 2018). "In the primary tumor, TNFα induces EMT and expression of IL12Rβ2 to promote tumor invasion and migration." (PMID 30218063, 2018). "Tumor necrosis factor-alpha is a critical pro-inflammatory cytokine produced by macrophages and was once considered an anti-tumor agent." (PMID 29467927, 2018). "Further studies utilizing TNF-α cell-specific conditional knockout mice or anti-TNF mAbs will address the exact role of TNF-α in immune cell activation and tumor suppression in this model." (PMID 29588627, 2018). "Factors in the tumor microenvironment contribute to the greater sensitivity of the tumor vasculature to TNF." (PMID 30170620, 2018). "The elevation of tumor invasion is supported by our sequencing results that demonstrated TNFα up-regulates invasion-related genes of MMP1, MMP9, MMP14, LAMB3, and FGF2 which all have been previously reported to increase OSCC cancer invasion." (PMID 30018735, 2018). "In this study, we have utilized clinical specimens and established cell lines to obtain innovative insights into the relationship occurring between expression of IFN-γ and TNF-α pro-inflammatory cytokines in PCa tissues, and tumor progression." (PMID 29896191, 2018).
tumor (continued). "PPARγ overexpression inhibits the activity of TNF-α and NFκB resulting in a reduction of tumor development." (PMID 29706964, 2018). "Th1 cells are anti-tumorigenic by virtue of either activating CD8 T cells or directly killing tumor cells by secreting TNF-α and/or IFN-γ." (PMID 29765907, 2018). "MD was employed for rationalizing the leading mechanisms involved in the interaction between tumor necrosis factor (TNFα) and tumor necrosis factor receptors (TNFRs), mediated by a constraining agent for tumor cells." (PMID 30674838, 2018). "For example, tumor necrosis factor (TNF)-α supports survival and proliferation of tumor cells and increase vascular permeability." (PMID 30200242, 2018). "The initial concept to use recombinant TNF as an anti-tumor agent was quickly followed by the idea to consider TNF as a drug target for inflammatory diseases." (PMID 29751683, 2018). "NF-κB, in turn, is known to induce TNFα, IL-1, IL-6 and IL-8 and thereby contributing to tumor cell growth an proliferation." (PMID 29930291, 2018). "In tumor cells, TNFα stimulates NF-κB signaling pathways to regulate motility, migration, invasion, and chemoresistance." (PMID 30356176, 2018). "SNAIL1 represses the production of pro-inflammatory cytokines IL-1α and TNFα and inhibits production of GM-CSF, a known stimuli of M1-like macrophages leading to a suppression of the pro-inflammatory response elicited by the tumor cells." (PMID 29593211, 2018). "TAMs harvested from tumor-bearing mice treated with 3-BP displayed enhanced tumoricidal activity and pro-inflammatory cytokine (IL-1, TNFα) production." (PMID 30619850, 2018). "This pathway is known to regulate expression of the tumor-promoting cytokines, IL-1, IL-6, and TNF-α." (PMID 30298062, 2018). "Together, these findings show docetaxel increases expression of multiple pro-lymphangiogenic factors, including VEGFC and TNF-α, in the 4T1 tumor microenvironment, and these changes can be mitigated by the addition of anti-VEGFR3 therapy." (PMID 29976154, 2018). "M1 macrophages itself were reported to suppress tumor growth and stimulate body immune response via secreted inflammatory cytokines, such as IL-12 and TNF-α." (PMID 30465444, 2018). "In our experimental conditions, we also observed that the TNF-α levels were significantly higher in the tumors of WT mice, which is consistent with the ability of TNF-α to induce inflammation and subsequent tumor development." (PMID 30112116, 2018). "Pro-inflammatory cytokines (e.g., TNF-α and IL-6) produced by tumor or host tissue due to tumor presence leads to both systemic and local inflammation in cancer." (PMID 29338749, 2018). "The cells displayed pro-inflammatory (IL-2, IL-8, and TNFα) and anti-inflammatory (IL-4 and IL-10) activities IL-2, IL-4, and IL-8 can promote the proliferation and survival of tumor cells by means of autocrine/paracrine signaling pathways." (PMID 29495627, 2018). "Systemic administration of TNFα can lead to hypotension and hepatotoxicity while IL-6 is known to be present in the tumor microenvironment, where it supports the survival and proliferation of cancer cells." (PMID 29632539, 2018). "We show that blocking EGFR with cetuximab inhibits the activation of several pathways downstream of EGFR and results in an increased production of inflammatory chemokines and attraction of T cells when the tumor cells are stimulated with IFNγ and TNFα." (PMID 30192802, 2018). "TNF is a multifunctional pro-inflammatory cytokine that belongs to the tumour necrosis factor superfamily and acts as a tumour repressor." (PMID 30065253, 2018). "Targeting tumor vasculature with TNF to optimize the tumor microenvironment increases the efficacy of the cytotoxic agent, either carried on the nanomedicine platform or administered separately." (PMID 30515264, 2018). "The TNF-α stimulation of the mesenchymal stem cells led to a dose-dependent increase in the expression of R/C in the tumor." (PMID 30174768, 2018).
tumor (continued). "TNF-α is a major mediator of proliferations and inflammations and its tumor-promoting action involves TNFR1 activation." (PMID 29352129, 2018). "NF-κΒ is downstream of TNF-α and other inflammatory cytokines produced in the tumor microenvironment, and is a major mediator of the tumor-promoting activity of inflammatory cytokines." (PMID 29467927, 2018). "Macrophages are important mediators in tumor defense by directly eliminating tumor cells by secreting the reactive nitrogen species nitric oxide and TNFα." (PMID 30647851, 2018). "TRAF2 overexpression also enhanced the level of tumour-derived TNFα, a known an inhibitory factor of osteoblast survival and differentiation." (PMID 29311633, 2018). "In the context of cancer, TNF-α neutralization was shown to delay tumor growth and decrease an MDSC accumulation." (PMID 30194424, 2018). "Recent study revealed that TNF-α blockade prevents death of tumor infiltrating T lymphocyte induced by anti-PD-1 as well as PD-L1 and TIM-3 expression." (PMID 30547012, 2018). "Classically activated M1 macrophages produce proinflammatory cytokine-like IL1-beta, and TNF-alpha to enhance the efficacy of chemotherapeutics and induce tumor regression." (PMID 30166607, 2018). "TNF-α plays the significant part in the formation of the large haemorrhaging area that appears within the tumor." (PMID 29568324, 2018). "In parallel, we compared tumor cell growth in vitro under constant dox-mediated Eed depletion alone or in combination with LPS plus TNF-α." (PMID 30487290, 2018). "Our study results showed that TNF-α correlated with M1 macrophages in stroma as well as the total number of M1 macrophages and M2 macrophages in tumor islets." (PMID 29361917, 2018). "We also detected the effect of ionomycin or parvalbumin on the anti-tumor activity of TNFα in a mice model." (PMID 29506556, 2018). "TNFR2 is a transmembrane receptor that can bind to TNF-α, a pleiotropic cytokine involved in regulating the tumor microenvironment." (PMID 29435163, 2018). "We report six pediatric rheumatology patients with neoplasms following anti-TNF exposure initiated during a period of more than 15 years." (PMID 29540190, 2018). "In fact in a cancer-environment, IL-10 would act like anti-apoptotic and tumor-growth factor, but during exercise it would act like anti-inflammatory cytokine, increasing the cortisol-level and inhibiting TNF-α." (PMID 29732034, 2018). "Functional testing further showed that these Tim3+CD8+ TILs exhibited reduced cell proliferation (Ki67) and cell activity and the production of effector cytokines (IFN-γ, IL-2, and TNF-α), indicating low anti-tumor activity." (PMID 30309387, 2018). "Such cultures are incubated with autologous tumor lysate and activated by a cocktail of agents combining TNFα, poly-ICLC (Hiltonoltm) and IFNα." (PMID 30268156, 2018). "Our data indicate that when SNAIL1 expression is activated in tumor cells, they produce less pro-inflammatory cytokines IL1α and TNFα and M1-like stimulating GM-CSF." (PMID 29593211, 2018). "Tumor cells secrete a number of soluble molecules, including interleukin-6 (IL-6) and tumor necrosis factor-α (TNF-α)." (PMID 29887927, 2018). "The role of TNF-α in the pathogenesis of OM is also unclear due to the fact that TNF-α can be produced both by tumor tissues and in reaction to tissue damaging factors." (PMID 28401452, 2018). "We recently used this model to show that TNFα increases degradation-dependent invasion in UMSCC1 cells, therefore we replicated the experiments here using using TNFα to promote invasion and compare tumour spheroid invasion in both cancer models." (PMID 30356830, 2018). "TNF-α can be produced by tumor cells, infiltrating immune cells and stroma cells in tumor microenvironment." (PMID 29559745, 2018). "During the malignant progress of tumors, tumor-related inflammatory cells are activated and secret several pro-inflammatory cytokines, including tumor necrosis factor, IL-1, IL-6, and IL-8." (PMID 29568406, 2018).